HTR1A (5-hydroxytryptamine receptor 1A)
Diseases named in the same sentence as HTR1A in open-access papers (continued):
Sharing a sentence is not in itself a finding about the gene and the disease.
breast carcinoma (continued). "However, when compared to normal breast tissue, HTR1A, HTR1B, HTR2A, HTR2B, HTR2C, HTR4, and HTR7 were suppressed in high malignancy breast cancer types, whereas they were highly expressed in low malignant breast cancer." (PMID 37795441, 2023). "In addition, to explore the antitumor effect of the demethylation drug combining with the HTR1A agonist, we first screened several of HTR1A‐agonist drugs and investigated their inhibition rate on LM2 breast cancer cells." (PMID 35199941, 2022). "Therefore, the combined treatment of HTR1A agonists with demethylation drugs such as 5‐aza‐2’‐deoxycytidine may significantly improve the expression of HTR1A and the survival of patients, which might provide a new approach for the treatment of breast cancer patients." (PMID 35199941, 2022). "In addition, the mRNA levels of HTR1B were not significantly changed in all breast cancer subtypes compared with normal breast tissue, and the mRNA for HTR1A/3B/5A were barely expressed." (PMID 37795441, 2023). "It is of great significance to clarify the function and mechanism of the depression‐related gene HTR1A in breast cancer, which might provide a new approach for triple‐negative breast cancer patients." (PMID 35199941, 2022). "Notably, previous results showed that the expression level of HTR1A in breast cancer tissues was significantly lower than that in paracancerous tissues, indicating that there was a significant negative correlation between HTR1A expression and the CpG site methylation level." (PMID 35199941, 2022).
Stroke (5 papers, 2009 to 2025). Sudden impairment of blood flow to a part of the brain due to occlusion or rupture of an artery to the brain. "Eight common genes were found across all three compounds and stroke: MAPK1, PRKCB, PRKCG, HDAC1, HTR1A, HTR2A, HTR2C, and HTR7." (PMID 41011194, 2025).
delirium (3 papers, 2016 to 2022). A disorder characterized by confusion; inattentiveness; disorientation; illusions; hallucinations; agitation; and in some instances autonomic nervous system overactivity. "As a result, much attention has been paid to the HTR1A because its activation in discrete brain regions appears to be a sufficient stimulus to elicit specific symptoms of delirium." (PMID 27760517, 2016). "The result showed that for control rats with saline treatment or scopolamine-induced delirium rats, the protein level and mRNA level of HTR1A were significantly higher in hippocampus and BLA than other brain regions." (PMID 27760517, 2016). "The serotonergic system may vary depending on the severity of delirium symptoms, but HTR1A antagonist treatment affecting the function of hippocampus can influence the modulation of a variety of neurophysiological changes." (PMID 27760517, 2016). "Meanwhile, the expression of HTR1A in hippocampus and BLA of scopolamine-induced delirium rats was significantly increased when compared with those of saline-treated rats." (PMID 27760517, 2016).
glioma (3 papers, 2021 to 2024). A benign or malignant brain and spinal cord tumor that arises from glial cells (astrocytes, oligodendrocytes, ependymal cells). "CXCL10, CCL13, SAA1, and CCL27 were more highly expressed in elderly, high‐grade, 1p19q non‐codel, IDH‐wildtype glioma patients, while SSTR5, CCL21, and HTR1A expressions were low in these malignant clinicopathological features of gliomas." (PMID 33503296, 2021). "In previous studies, the molecular mechanisms of HTR1A, CCL13, CCL21, and CCL27 in gliomas remained unclear." (PMID 33503296, 2021). "The result indicated that HTR1A was expressed at low levels in ovarian serous cystadenocarcinoma (OV) and glioblastoma multiforme (GBM) while being highly expressed in brain lower grade glioma (LGG)." (PMID 39766808, 2024).
triple-negative breast carcinoma (3 papers, 2023 to 2025). An invasive breast carcinoma which is negative for expression of estrogen receptor (ER), progesterone receptor (PR), and human epidermal growth factor receptor 2 (HER2). "HTR1A has the potential to impede the advancement of triple-negative breast cancer via the TGF-β signaling pathway." (PMID 40452916, 2025). "A recent study reported that HTR1A inhibited the progression of triple-negative breast cancer via TGF-β canonical and noncanonical pathways and HTR1A agonists significantly improved patient survival." (PMID 37795441, 2023).
asthma (2 papers, 2013 to 2024). "Clinical studies with inhibitors of individual HTRs such as HTR1A or HTR2A have had only a small benefit for asthma, but this may reflect involvement of multiple HTRs during asthma." (PMID 38845678, 2024).
cholangiocarcinoma (2 papers, 2021 to 2024). A carcinoma that arises from the intrahepatic biliary tree (intrahepatic cholangiocarcinoma) or from the junction, or adjacent to the junction, of the right and left hepatic ducts (hilar cholangiocarcinoma). "HTR1A is widely involved in many human tumor types, including bladder, prostate, small cell lung, colorectal, and cholangiocarcinoma." (PMID 34600545, 2021).
fibromyalgia (2 papers, 2022). A chronic disorder of unknown etiology characterized by pain, stiffness, and tenderness in the muscles of neck, shoulders, back, hips, arms, and legs. "Furthermore, gene-to-gene interactions between the mu-opioid receptor (MOP) gene (OPRM1) and the serotonin transporter (5-HTT) or 5-HT1A (HTR1A) genes had antagonistic effects on endogenous descending pain modulation in healthy subjects and in fibromyalgia patients." (PMID 35408749, 2022).
glaucoma (2 papers, 2019 to 2021). Increased pressure in the eyeball due to obstruction of the outflow of aqueous humor. "These 13 glaucoma-associated genes can be divided into three functional groups: phototransduction-related genes (GNGT1, OPN1SW, PDE6A, PDC, CRX, CNGB1, GUCY2F), glutamate receptor (GR) genes (GRIN2B, GRIK3, GRIK4), and 5-hydroxytryptamine receptor (HTR) genes (HTR1A, HTR1E, HTR7)." (PMID 33874942, 2021). "For the three HTRs (HTR1A, HTR1E, and HTR7), limited works have been undertaken to link them with glaucoma." (PMID 33874942, 2021).
Headache (2 papers, 2017 to 2022). Cephalgia, or pain sensed in various parts of the head, not confined to the area of distribution of any nerve. "The expression of 5‐HT receptor genes, Htr1a, Htr1f, and Htr2c, was found to be activated in this study and contributed to headaches and behavioral inhibition in mice." (PMID 36514756, 2022).
irritable bowel syndrome (2 papers, 2021 to 2024). Irritable bowel syndrome (IBS) is a chronic functional condition of the lower gastrointestinal (GI) tract characterized by abdominal pain or discomfort and disordered bowel habit (diarrhea, constipation, or fluctuation between the two). "Tegaserod and alosetron were initially used to treat irritable bowel syndrome, but they have been withdrawn due to cardiovascular complications associated with off-targets HTR1A and HTR2B, as inferred by our model." (PMID 39570605, 2024). "A study on irritable bowel syndrome rat model shows that resveratrol had inhibitory activity on the 5-hydroxytryptamine receptor 1A (5-HT1A), thus improving the brain–gut axis." (PMID 34575524, 2021).
lung cancer (2 papers, 2016 to 2019). A malignant neoplasm involving the lung. "It is interesting to note that genes such as C5AR1, CHRNA4 and HTR1A from the neuroactive ligand receptor pathway have been reported in association with PAH, lung cancer, COPD and idiopathic pulmonary fibrosis." (PMID 31324852, 2019).
lymphoid cancer (2 papers, 2019 to 2024). "While cell lines from certain tissues seem to be equally inhibited by top GPCR drugs (e.g., lung), others are sensitive to specific GPCR drugs, such as lymphoid cancer cells, which are particularly inhibited by DRD2, CHRM1, CHRM2, HTR1A, and HTR2A antagonists." (PMID 38723607, 2024).
Asperger Syndrome (1 paper, 2023). "The aim of this research was to analyze the methylation profile of four well-known genes involved in neurodevelopment (BDNF, RELN, MTHFR and HTR1A) in the mothers of forty-five age-matched AS (Asperger Syndrome), ADHD (Attention Deficit Hyperactivity Disorder) and typically developing children." (PMID 36980856, 2023).
coronary artery atherosclerosis (1 paper, 2021). "Comparing the targets of the herbal strategies and three existing drugs (atenolol, pravastatin and propranolol) and the symbols of coronary artery atherosclerosis, we discovered that MAOA, HTR1A, and ABCG2 are overlapping in the three groups." (PMID 34012683, 2021).
gastritis (1 paper, 2025). Inflammation of the stomach. "HTR1A was upregulated in the stomachs of mice chronically infected with H. pylori SS1 (3 weeks) compared to uninfected controls, whereas HTR2B was upregulated only in acutely infected mice (3 days), consistent with a role for 5-HT signalling in the development of gastritis." (PMID 40869057, 2025).
invasive breast carcinoma (1 paper, 2023). A carcinoma that infiltrates the breast parenchyma. "In two datasets, the mRNA expression levels of HTR1A were significantly upregulated in invasive lobular breast carcinoma and invasive breast carcinoma stroma." (PMID 37795441, 2023).
keloid (1 paper, 2021). An irregularly shaped, elevated mark on the skin caused by deposits of excessive amounts of collagen during wound healing. "The identification of GNG13 and HTR1A as hub genes is consistent with keloids sharing some characteristics with cancer." (PMID 34600545, 2021). "The mRNA levels of NPY, ADCY8, GNG13 and HTR1A were significantly augmented in keloid compared with normal skin samples ***p < 0.001." (PMID 34600545, 2021). "GNG13, ADCY8, NPY and HTR1A may act as core genes in keloid formation and these core genes establish relationship with SP1 and miRNA (hsa-mir-372, hsa-mir-20, hsa-mir-10b), which may influence multiple signaling pathways in the pathogenesis of keloid." (PMID 34600545, 2021).
liver cirrhosis (1 paper, 2025). "It was demonstrated that the expression of HTR1A was significantly increased in the hypertensive portal vein of rats with a PH model and in patients with liver cirrhosis." (PMID 39997697, 2025).
mesothelioma (1 paper, 2022). A usually malignant and aggressive neoplasm of the mesothelium which is often associated with exposure to asbestos. "In all three mesothelioma cell lines, both CBD and CBG robustly upregulated mRNA for the cannabinoid CB1 receptor (CNR1), G protein-coupled receptor 55 (GPR55) and the 5-HT1a receptor (HTR1A)." (PMID 35954477, 2022).
metastatic prostate carcinoma (1 paper, 2024). A carcinoma that arises from the prostate gland and has spread to other anatomic sites. "PAAD progression involves various serotonin receptor subtypes at distinct tumor phases, with significant HTR1A and HTR1B expression observed in aggressive PAAD characterized by high Gleason scores and metastatic prostate cancer." (PMID 39766808, 2024).
pancreatic adenocarcinoma (1 paper, 2024). "Our findings revealed elevated HTR1B levels in advanced pancreatic adenocarcinoma (PAAD) but did not demonstrate a correlation between HTR1A and PAAD tumor stages." (PMID 39766808, 2024).
psychiatric disorder (34 papers, 2006 to 2025). A disorder characterized by behavioral and/or psychological abnormalities, often accompanied by physical symptoms. "Therefore, we solidly demonstrated that a significantly increased CEBPB that recognizes the HTR1A strongly inhibited the level of this gene and leaded to the susceptibility to the mental illness." (PMID 31614865, 2019). "It is becoming increasingly necessary to understand the effects of the regulatory region in the HTR1A on receptor expression, which may further clarify the pathogenesis of psychiatric diseases." (PMID 31614865, 2019). "Moreover, C/EBPβ could strongly inhibit the level of the HTR1A gene (gene of 5-HT1A receptor) and resulted in the susceptibility to mental illness." (PMID 36578534, 2022). "Whilst speculative, it is also potentially of relevance that HTR1A protein expression is upregulated in the brains of schizophrenics and variants in both HTR1A and SLIT3 are associated with psychiatric disorders, known to involve dopaminergic and serotoninergic pathways." (PMID 32209227, 2020).
cancer (13 papers, 2018 to 2024). A tumor composed of atypical neoplastic, often pleomorphic cells that invade other tissues. "HTR1A exhibited low expression across various cancers while elevated levels of HTR1A were associated with better overall survival in LGG and GBMLGG." (PMID 39766808, 2024). "Conversely, HTR1A/1E/4/5A/5B were found to be expressed less in a pan-cancer context." (PMID 39766808, 2024). "In pan-cancer, high expression of HTR1B/1F/2B/4/7 was positively correlated with the expression of PD-1, PD-L1, and CTLA4 while the expression of HTR1A was negatively correlated with the expression of PD-1, PD-L1, and CTLA4 in GLB, LGG, SARC, OV, and PAAD." (PMID 39766808, 2024). "In the case of G3 cancer, a decrease in HTR2B expression and the overexpression of HTR1A and HTR1F were also noted." (PMID 34768392, 2021). "Our study found for the first time that HTR1A simultaneously inhibits the TGF‐β/TβRII/Smad canonical signaling pathway and TGF‐β/TβRII/MEK/ERK/c‐Myc noncanonical signaling pathway, which play significant roles in cancer development." (PMID 35199941, 2022).
tumor (11 papers, 2010 to 2025). "Extensive further studies are needed to verify the connection between HTR1A and tumor progression in PAAD." (PMID 39766808, 2024). "The results indicated that HTR1A may function as a tumor suppressor." (PMID 35199941, 2022).
neurological diseases (7 papers, 2015 to 2025). "Among the others, the activation of the 5-hydroxytryptamine receptor 1A (5-HT1A) is considered as one of the main mechanisms underlying the neuroprotective effects of CBD in neurological diseases." (PMID 32443623, 2020).
HTR1A also shares sentences with these, for which no sentence is quoted: Dyskinesia (22 papers); Parkinson disease (20); psychosis (12); serotonin syndrome (12); autism (10); generalized anxiety disorder (8); sexual dysfunction (8); memory impairment (7); migraine (7); panic disorder (7); colitis (5); Alzheimer disease (4); Anorexia (4); autism spectrum disorder (4); neuroblastoma (4); Rett syndrome (4); behavioral disorders (3); central nervous system diseases (3); cognitive decline (3); alcohol abuse (2); anorexia nervosa (2); Arrhythmia (2); Arthritis (2); attention deficit-hyperactivity disorder (2); brain injury (2); bruxism (2); cholestasis (2); epileptic seizures (2); fragile X syndrome (2); glioblastoma (2).
A further 119 diseases each share a sentence with HTR1A in 2 papers or fewer.